TNF (tumor necrosis factor)
Diseases named in the same sentence as TNF in open-access papers (continued):
Sharing a sentence is not in itself a finding about the gene and the disease.
small cell lung carcinoma (60 papers, 2013 to 2025). Small cell lung cancer (SCLC) is a highly aggressive malignant neoplasm, accounting for 10-15% of lung cancer cases, characterized byrapid growth, and early metastasis. "In the use case of adenocarcinoma vs small cell lung cancer, the t-test results indicated that TNF and NFKB signaling pathways were major distinguishing factors." (PMID 38959284, 2024). "Applying the MSigDB autoencoder to the differential analysis of adenocarcinoma vs small cell lung cancer, identified complement and TNF-alpha signaling via NFKB as major distinguishing factors." (PMID 38959284, 2024). "The upregulated DEGs were in KEGG enriched in TNF signaling pathways, small-cell lung cancer, etc., and in sister chromatid segregation and regulation of nuclear division in GO." (PMID 35919033, 2022). "KEGG pathway analysis demonstrated that these DEGs were enriched in ECM-receptor interaction, cell adhesion molecules (CAMs), chemical carcinogenesis, TNF signaling pathway, small cell lung cancer, mismatch repair, phagosome, etc.." (PMID 33790390, 2021). "Among them, the PI3K-Akt signaling pathway, TNF signaling pathway, and small cell lung cancer have been reported to be related to cancer." (PMID 33147797, 2020). "BEZ235 treatment upregulated transcripts and showed a significant enrichment for genes involved in pathways in cancer, TNF signaling and small-cell lung cancer." (PMID 33316942, 2020). "In a small cell lung cancer xenograft model, it has been shown that cancer cells rolled in vivo on tumor necrosis factor α-(TNFα-) treated vessels, although the rolling velocity was seven times faster than that of leukocytes." (PMID 27148485, 2016). "They suggested that BAL and blood cells from patients with small cell lung carcinoma secreted significantly less cytokines (IL-1, IL-6 and TNF-α) than BAL and blood cells from patients with NSCLC." (PMID 26316944, 2014). "The enrichment results suggest that the antimicrobial mechanism of Ea73 CFS may be closely related to pathways such as small cell lung cancer, the IL-17 signaling pathway, the TNF pathway, and the C-type lectin receptor signaling pathway." (PMID 41357751, 2025). "Moreover, the up-regulated genes in blue modification pattern were mainly enriched in small cell lung cancer, TNF signaling pathway, prion disease, diabetic cardiomyopathy, and ECM-receptor interaction pathways." (PMID 35910226, 2022). "Furthermore, PTGS2 was directly enriched in related inflammation pathways, such as the TNF signaling pathway and the IL-17 signaling pathway, and in small cell lung cancer." (PMID 34211564, 2021). "YKL-5-124, a potent CDK7 inhibitor, activates IFN-γ signaling and induces TNF-a and CXCL9/10 in small-cell lung cancer." (PMID 40175357, 2025). "BAL and whole blood cells from patients with small cell lung carcinoma and NSCLC cancer were compared in their secretion of IL-1, IL-6, and TNF-α." (PMID 26316944, 2014). "Additionally, ten KEGG pathways, including the human papillomavirus infection, ECM-receptor interaction, small cell lung cancer, TGF-β signaling pathway, PI3K-Akt signaling pathway and TNF signaling pathway were determined." (PMID 32571304, 2020). "We observed that these signaling pathways are evidently related with human tumors or cancer, including small cell lung cancer as they are involved in related processes, such as apoptosis, neurotrophin, FoxO, MAPK, PI3K/Akt, ErbB, TNF and Toll-like receptor signaling pathway." (PMID 30979098, 2019).
fibromyalgia (59 papers, 2010 to 2026). A chronic disorder of unknown etiology characterized by pain, stiffness, and tenderness in the muscles of neck, shoulders, back, hips, arms, and legs. "In another pilot clinical trial, treatment with naltrexone resulted in marked inhibition of proinflammatory cytokines levels including IL-1β, IL-6 and TNF-α and reduction of fibromyalgia-associated nociplastic pain." (PMID 37069462, 2023). "(III) A case-control study showing plasma levels of MCP-1, VEGF and TNF-alpha significantly lower in AAT deficiency subjects with fibromyalgia than in controls." (PMID 21486454, 2011). "Interestingly, levels of microglial-derived TNFα; correlate with clinical parameters of fibromyalgia, suggesting a possible mechanism underlying fibromyalgia symptomatology." (PMID 32742693, 2020). "TNF-α from microglia may be a key factor underlying the complex pathology of fibromyalgia." (PMID 28928366, 2017). "Proinflammatory cytokines such as IL-1β and TNF-α are elevated in fibromyalgia (FM), contributing to neuroinflammation and central sensitization, which amplifies pain perception and is linked to fatigue and cognitive dysfunction." (PMID 41002443, 2025). "In fibromyalgia, reduced miR-143 expression has been associated with the loss of its anti-inflammatory function, since miR-143 typically suppresses COX-2 and TNF-α." (PMID 41010614, 2025). "Human studies in fibromyalgia have demonstrated increased Th1 type signature of CD4+ T cell subpopulations, with associated increases in interferon-gamma (IFNγ) and TNFα production and correlation with disease severity." (PMID 40002538, 2025). "Research has indicated elevated levels of IL-6, IL-1β, IL-8, and/or tumor necrosis factor (TNF)-α in fibromyalgia." (PMID 40172661, 2025). "The interrelationship between fibromyalgia and inflammatory biomarkers, such as IL-6, IL-8, and TNF-α, has been the subject of an increasing number of studies." (PMID 39202077, 2024). "Increased levels of pro-inflammatory cytokines, such as TNF-α, IL-1β and IL-6 and their mediators, were detected in the suffering animals compared to the controls, confirming the key role of inflammation in fibromyalgia." (PMID 36979771, 2023). "A prior work suggested that microglia in cases suffering from fibromyalgia were oversensitive to ATP, which induced TNF-α expression." (PMID 37069462, 2023). "A previous randomized controlled trial found that plasma levels of TNF-α and IL-6 were elevated in fibromyalgia patients." (PMID 37069462, 2023). "Remarkably, there was a direct correlation between the intensity of fibromyalgia pain and the ATP-induced overexpression of TNF-α." (PMID 37069462, 2023). "In some studies conducted on the plasma of patients with fibromyalgia, an increase in pro-inflammatory cytokines, such as IL-6, interleukin-8 (IL-8), IL-1β, and TNF-α, was found." (PMID 35566735, 2022). "Several studies have reported that serum TNF-α is significantly higher in humans experiencing chronic pain, such as people with sciatica, fibromyalgia, lumbar disc herniation, and low back pain." (PMID 35061744, 2022). "In fact, patients with fibromyalgia showed an increase in interleukin and TNF-α levels in serum and plasma, which contribute not only to the exacerbation of inflammatory response but also to pain." (PMID 34445126, 2021). "CRP and TNF-α have also been found to be significantly higher in individuals with fibromyalgia compared to healthy controls and have been found to correlate positively with pain and fatigue." (PMID 32878326, 2020). "Elevated plasma levels of IL-17 as well as tumor necrosis factor (TNF) have been observed in patients diagnosed with fibromyalgia." (PMID 33042712, 2020). "It is worth mentioning that one study found elevated plasma levels of TNFα, substance P and corticotropin-releasing hormone in fibromyalgia patients when compared with controls." (PMID 33042712, 2020).
fibromyalgia (continued). "The objective of this study was to verify the effects of aerobic exercise associated with tryptophan (TRP) supplementation on hyperalgesia, as well as on cortisol, IL-6 and TNF concentrations in female rats with experimental fibromyalgia (FM)." (PMID 30785911, 2019). "At basal level, TNF-α gene expression levels are significantl lower in iMG cells from patients with fibromyalgia." (PMID 28928366, 2017). "Further, the release of IL-1β, IL-6, and TNF during moderate exercise has also been shown to be higher in patients with fibromyalgia than healthy controls." (PMID 26624891, 2015). "The role of TNFα in pain was reported by many clinical studies of chronic pain, neuropathic pain and fibromyalgia syndrome." (PMID 20937109, 2010). "Recent studies identify an imbalance in cytokine levels in fibromyalgia patients, characterized by elevated tumor necrosis factor-alpha (TNF-α), interleukin-6 (IL-6), and interleukin-8 (IL-8), with serum concentrations of IL-6 and IL-8 significantly correlating with disease severity." (PMID 40407467, 2025). "In particular, studies have demonstrated elevated expression of pro-inflammatory cytokines such as IL-6, IL-8, and TNF-α in monocytes from fibromyalgia patients, suggesting monocyte activation may contribute to systemic and central sensitization processes." (PMID 41517404, 2025). "In fibromyalgia (FM), serum levels of pro-inflammatory cytokines such as interleukin-6 (IL-6), interleukin-8 (IL-8), interleukin-1 beta (IL-1β), and tumor necrosis factor-alpha (TNF-α) are frequently elevated, whereas concentrations of anti-inflammatory cytokines are typically reduced." (PMID 41002443, 2025). "Interestingly, fibromyalgia patients treated with hyperbaric therapy demonstrated reductions in circulating Th1 cells, TNF-α, IFN-γ, and serotonin levels, and disease severity." (PMID 40002538, 2025). "LDN has been demonstrated to block TLR-4 in macrophages and microglia, inhibit or reduce T-cell proliferation and increase phagocytic activity of macrophages by raising IL-2 and TNF-α concentration and is therefore considered effective in chronic inflammatory disorders like fibromyalgia." (PMID 40337423, 2025). "The finding of elevated levels of these neuropeptides alongside IL-6 and TNF in fibromyalgia patients raises the possibility of mast cell origin of the inflammatory cytokine signature of fibromyalgia and supports a bidirectional interaction between pain-mediating substance P and mast cells." (PMID 40002538, 2025). "A decrease in TNF-α was not evident after SAP, SAP-SP, or HA treatment; this result might be explained by the fact that TNF-α is a less specific marker than IL-1β, considering that TNF-α levels in OA cannot be discriminated from that in fibromyalgia." (PMID 37143133, 2023). "In a group of female fibromyalgia patients, the M1/M2 imbalance was corrected by an eight-month pool-aquatic exercise program resulting in lower levels of TNFα and increased IL-10 levels, producing anti-inflammatory effect and enhancing the quality of patients’ life." (PMID 37069462, 2023). "MCs could release proinflammatory cytokines, chemokines, and chemical mediators when they are involved in the inflammation of fibromyalgia, and the level of TNF induced by MCs elevates in fibromyalgia." (PMID 30728750, 2019). "At the same time, IL-37 could inhibit the inflammation response of IL-1 family members and TNF in fibromyalgia." (PMID 30728750, 2019). "In addition, TNF-α protein levels are also significantly higher in the culture supernatant of iMG cells from patients with fibromyalgia." (PMID 28928366, 2017). "Interestingly, gene expression of TNF-α is significantly higher in iMG cells from patients with fibromyalgia." (PMID 28928366, 2017). "Interestingly, iMG cells of fibromyalgia showed hyperresponsiveness to extracellular ATP and increases in the proinflammatory cytokine TNF-α." (PMID 28928366, 2017).
fibromyalgia (continued). "Interestingly, there was a moderate correlation between ATP-induced upregulation of TNF-α expression and clinical parameters of subjective pain and other mental manifestations of fibromyalgia." (PMID 28928366, 2017). "In conclusion, microglia-derived TNF-α may be a possible key modulating factor of fibromyalgia, and future translational research is needed to establish a novel diagnostic system and therapeutic strategies against fibromyalgia." (PMID 28928366, 2017). "TNF-α may also contribute to fibromyalgia because TNF-α application into the normal masseter muscle evoked a long-lasting reduction of the mechanical threshold of muscular Aδ-fibers." (PMID 25606597, 2014). "Mast cells, found in an increased number of the skin of fibromyalgia patients, degranulate, releasing various pro-inflammatory, neurostimulatory, and vasoactive mediators, including but not limited to histamine, bradykinin, prostaglandins, TNF, serotonin, and endothelial growth factors." (PMID 40002538, 2025). "It is conceivable that mediators of inflammation, like interleukin 1β, IL-6 and TNF-α, that are elevated in the brain of animals with acid saline-induced fibromyalgia may activate IDO, which, in the presence of an excess of Trp, would lead to increased KYN levels in the brain." (PMID 39404410, 2024). "Previous studies have showed that IL-37 is also involved in the improvement of inflammation due to mast cell activation induced by fungi and the inhibition of proinflammatory IL-1 family members and TNF by this inhibitory cytokine in fibromyalgia could have a therapeutic effect." (PMID 31686988, 2019). "Furthermore, patient-reported SpA measures are known to differentiate poorly between symptoms related to SpA or CWP, with generally worse outcomes among patients with such comorbidity, and poorer adherence to anti-TNF therapy was also recently reported in SpA patients with concurrent fibromyalgia." (PMID 26703005, 2015). "Fibromyalgia has been genetically linked to the HLA region (6p21.3) 63, which includes several genes associated with Notch signalling (e.g. Notch4, FKBP5, TNXB, MTCH1 and TNF-a) or with stem cell maintenance and proliferation (e.g. POU5F1, Flot1, MAPK14, Rgl2 and Rab44)." (PMID 25164209, 2014). "While no linkage was established between vitamin K levels and FM, positive correlations were found between IL-6 and the Fibromyalgia Impact Questionnaire (FIQ), and between TNF-alpha and physical role difficulty." (PMID 38257075, 2024). "Indeed, there is evidence that high serum concentrations of cortisol associated with stress might worsen ache in individuals with fibromyalgia and potentialize the pro-nociceptive influence of inflammatory markers like IL-6 and tumor necrosis factor-alpha (TNF-α)." (PMID 39404410, 2024). "The expression of tumor necrosis factor (TNF)-α at mRNA and protein levels significantly increased in ATP-stimulated iMG cells from patients with fibromyalgia compared to cells from healthy individuals." (PMID 28928366, 2017). "This may be related to overlapping inflammatory profiles, including elevated levels of IL-1β, IL-6, TNF-α, and IL-17, which are characteristic of FMF, CD, and fibromyalgia." (PMID 41451232, 2025). "Similarly, infliximab administration to rats with reserpine-induced fibromyalgia inhibited microglial stimulation via decreasing the expression of P2X7R and its downstream p38-MAPK, resulting in low levels of IL-1β, IL-6 and TNF-α." (PMID 37069462, 2023). "FMS had been recently recognized as one of the main predictors of drug discontinuation in PsA patients on TNF inhibitors, with almost no PsA patients with comorbid fibromyalgia achieving clinical disease remission upon anti-TNF therapy." (PMID 35833126, 2022). "In support of this concept, there was also a significant association between TNF-α levels and the WPI in ANA+ subjects without fibromyalgia, which was largely driven by the SARD sub-group." (PMID 31685018, 2019).
fibromyalgia (continued). "It has been shown that serum TNFα is increased in patients with fibromyalgia and non-specific low back pain." (PMID 30675683, 2019). "Although plasma cytokines were not analyzed in this study, muscle levels of IL-6 and IL-8 (but not IL-1β or TNF) were reported higher than plasma levels in patients with fibromyalgia, supporting that they are produced in the muscle." (PMID 28243900, 2017). "Finally, one review found that the difference in levels of IL-6, IL-8, TNF-α, and brain-derived neurotrophic factor (BDNF) may have the potential to be used for stratification of patients with fibromyalgia into subgroups for future targeted therapies." (PMID 41598488, 2026). "Thus, this study indicates that IL-1β, IL-6, IL-8, and TNF do not seem to play an important role in maintenance of muscle pain in fibromyalgia." (PMID 26624891, 2015). "The levels of TNF did not change during contractions in patients with fibromyalgia, but increased in controls (P < .001) and were significantly higher compared to patients with fibromyalgia (P = .033)." (PMID 26624891, 2015). "We believe that the somatic symptoms component of the ACR-2011 fibromyalgia criteria may best distinguish those with/without fibromyalgia and indeed, there is evidence that symptoms severity score is a predictor of non-response to TNF inhibition." (PMID 32556474, 2020).